IL1R2 (interleukin 1 receptor type 2)
Diseases named in the same sentence as IL1R2 in open-access papers (continued):
Sharing a sentence is not in itself a finding about the gene and the disease.
colorectal cancer (5 papers, 2021 to 2025). A primary or metastatic malignant neoplasm that affects the colon or rectum. "We examined tumor progression in wild-type and IL-1R2-deficient mice using an AOM/DSS-induced colitis-associated colorectal cancer model treated with combined ICIs therapy." (PMID 40767963, 2025). "Specifically, we examined tumor progression in wild-type and IL-1R2 knockout mice in a colitis-associated colorectal cancer model induced by AOM/DSS." (PMID 40767963, 2025). "Meanwhile, in colorectal cancer, IL1R2 is involved in activating IL6, VEGFA, and MEK/ERK, promoting cell proliferation and metastasis, promoting tumor angiogenesis, and enhancing tumor drug resistance." (PMID 37728418, 2023). "Moreover, the level of IL-1R2 ininfiltrating Treg cells is higher in colorectal cancer tissues than in normaltissues." (PMID 33704402, 2021).
endometriosis (5 papers, 2010 to 2023). The growth of functional endometrial tissue in anatomic sites outside the uterine body. "IL-1R2, the decoy form of the receptor has also been identified as deficient in human endometriosis, which is thought to be an IL-1β-induced pathology." (PMID 20066156, 2010).
Hypertension (5 papers, 2021 to 2025). The presence of chronic increased pressure in the systemic arterial system. "We observed IL-6 and TNF-α were also positively related to Clostridium-innocuum-group, which was classified as a risk factor for hypertension, with IL-1R2 (an inflammation-associated receptor) being identified as a significant mediator." (PMID 41154794, 2025). "Using the two-step IL-1R2 method, we determined that IL-1R2 acts as a mediator in the causal relationship from the Clostridium innocuum group to hypertension (b = 0.0007, 95%CI: 0.0002–0.0011)." (PMID 38089928, 2023). "Our findings indicate that IL-1R2 could bridge the causal link between intestinal microorganisms and hypertension, laying the groundwork for exploring the intersection of hypertension and inflammation and potentially inspiring future therapeutic strategies for hypertension." (PMID 38089928, 2023). "This analysis underscores the link between gut microbiota and hypertension, highlighting the mediating role of IL-1R2." (PMID 38089928, 2023). "Our research confirms a genetic causal relationship between specific gut microbes and hypertension, emphasizing the potential mediating role of interleukin-1 receptor type 2 (IL-1R2) and offering insights for clinical hypertension interventions." (PMID 38089928, 2023). "Our findings provide genetic evidence of the connection between the gut microbiome, IL-1R2, and hypertension." (PMID 38089928, 2023). "Mediation MR results suggest that IL-1R2 may account for 14.07% of the effect that the Clostridium innocuum group has on hypertension." (PMID 38089928, 2023). "Given our earlier findings that established connections between “microbial taxa → hypertension” and “microbial taxa → IL-1R2”, we postulated that IL-1R2 may potentially mediate the relationship between microbial taxa and hypertension." (PMID 38089928, 2023). "While the link between hypertension and inflammation is well acknowledged, to the best of our knowledge, no current studies delve into the relationship between IL-1R2 and hypertension." (PMID 38089928, 2023).
lung carcinoma (5 papers, 2017 to 2024). "The increase level of IL-1R2 has been reported to be associated with poor prognosis in lung cancer, and the increase level of IL-1 was associated with the development of chronic obstructive pulmonary disease (COPD)." (PMID 34194423, 2021). "In summary, this is an exploratory study concerning the association of IL‐1R2 SNPs with the susceptibility of lung cancer." (PMID 30895747, 2019). "IL‐1R2 rs2072472 polymorphism increased the risk of lung cancer; conversely, the rs3218977 polymorphism reduced the susceptibility of lung cancer." (PMID 30895747, 2019). "The expression analysis of IL‐1R2 mRNA and annotation of the functional significance of the variants are needed to clarify the genetic mechanism underlying lung cancer in the future." (PMID 30895747, 2019). "We used the chi‐squared test, genetic model analysis, Haploview analysis, and multifactor dimensionality reduction (MDR) to evaluate the potential association between IL‐1R2 polymorphisms and lung cancer susceptibility." (PMID 30895747, 2019). "Bioinformatics analyses were conducted to analyze the expression level of IL‐1R2 and its association with the overall survival of lung cancer." (PMID 30895747, 2019). "In this case–control study, we successfully genotyped six SNPs in the IL1‐R2 gene and found that rs2072472, rs719250, rs11674595, and rs3218977 were related to the risk of lung cancer." (PMID 30895747, 2019). "Pro‐inflammatory cytokines (IL‐6, IL‐8, TNF‐α) and anti‐inflammatory cytokines (IL‐1RA, IL‐1R2) have been shown to be prospectively associated with increased lung cancer risk (Mario, Giovanny, Pedro, Norma, & Oscar, 2016)." (PMID 30895747, 2019). "In the current study, we aimed to investigate IL‐1R2 variants and their association with the susceptibility of lung cancer in a Chinese Han population using a case–control study." (PMID 30895747, 2019). "Our results found that rs3218977 in IL‐1R2 was associated with a decreased risk of lung cancer, especially in patients with lung squamous cell carcinoma." (PMID 30895747, 2019). "In silico, we found that IL‐1R2 gene expression is downregulated in lung cancer, whereas high expression of IL‐1R2 is associated with a poor overall survival for lung cancer." (PMID 30895747, 2019). "Combined with the previous studies, this association may be a promising starting point for a functional profile of the IL1‐R2 gene and increased understanding of the biological processes associated with lung cancer formation and progression." (PMID 30895747, 2019). "Given the expression and survival data of IL‐1R2 in lung cancer, polymorphisms in the IL‐1R2 gene might contribute to lung cancer risk." (PMID 30895747, 2019). "Moreover, IL‐1R2 high expression was found to be associated with lung cancer patients (hazard ratio = 1.37; 95% CI: 1.21–1.55; p = 1.1e‐06) based on Kaplan–Meier plotter." (PMID 30895747, 2019). "The findings further highlight that the polymorphisms in the IL1‐R2 gene may contribute to lung cancer susceptibility in the Chinese Han population." (PMID 30895747, 2019). "Our study provides evidence about the potential role of the IL1‐R2 variants in lung cancer risk." (PMID 30895747, 2019). "However, the role of IL‐1R2 polymorphisms in patients with lung cancer has yet to be fully elucidated." (PMID 30895747, 2019). "Our results suggest that genetic variants of IL‐1R2 may play a role in lung cancer susceptibility." (PMID 30895747, 2019). "Interleukin‐1 receptor 2 (IL‐1R2), as an anti‐inflammatory cytokine, is involved in the pathogenesis and progression of lung cancer." (PMID 30895747, 2019). "A number of established lung cancer oncogenes have also been included in the classifier, such as IL1R2, JUNB, EGFR, SOX9, FOSB, and JUND." (PMID 27935865, 2017). "The lung cancer-specific cfRNAs IL1R2 and CLEC4E are related to immune regulation." (PMID 35816095, 2022).
lung carcinoma (continued). "In addition, our results indicated that the IL‐1R2 mRNA level was downregulated in lung cancer patients, whereas the high expression of IL‐1R2 was related to a poor prognosis in lung cancer." (PMID 30895747, 2019). "We speculated that IL‐1R2 plays an important role in the progress and prognosis of lung cancer, but more studies are needed to validate." (PMID 30895747, 2019). "Studies based on variants in the IL‐1R2 gene are infrequent, and there is no finding of the association between the IL‐1R2 SNPs and lung cancer risk in previous studies." (PMID 30895747, 2019). "However, no previous study has investigated the association between lung cancer risk and IL‐1R2 polymorphisms." (PMID 30895747, 2019).
lupus (5 papers, 2009 to 2021). "Among those genes, IL10 and IL1R2 genes present a range of methylation-regulated domain variance in lupus." (PMID 28785369, 2017). "An epigenetic signature has also been identified for IL1R2 promoter in systemic lupus erythematosus (SLE)." (PMID 26246860, 2015). "Together, common characteristics of lupus appear to be upregulation of members of the IL-1 family such as IL-1α and IL-1β and IL1R2, of the TNF/death receptor family such as TNF receptor II (TNFRSF1B), TRAIL (TNFSF10), and its decoy receptors, and a gene signature of IFN-α/β-regulated genes." (PMID 19884985, 2009). "An example of “epigenetic DNA methylation” (VariO:0157) is decreased methylation of the interleukin 1 receptor type 2 gene, IL1R2, which is a suppressor for IL1 signalling that leads to downregulation of IL1 and can be used as a biomarker for lupus." (PMID 30591019, 2018).
myocardial ischemia (5 papers, 2017 to 2025). A disorder of cardiac function caused by insufficient blood flow to the muscle tissue of the heart. "IL-1R2 is elevated in patients after acute coronary syndrome and in mice after cardiac ischemia and reperfusion (I/R) injury." (PMID 38051583, 2024). "Some studies have suggested that IL-1R2 plays a role inregulating monocyte accumulation during myocardial ischemia/reperfusion injury." (PMID 39076182, 2022). "Interestingly, six out of the seven most differentially expressed IZ genes (IL8, ARG1, S100A12, CTSL, IL1R2, S100A8) identified in our study have been previously reported in myocardial ischemia, confirming the validity of our chip analysis." (PMID 28977827, 2017).
Obesity (5 papers, 2018 to 2024). Accumulation of substantial excess body fat. "Thus, future work could test for correlation between serum IL-1R2 level and age or obesity, and if this in part could explain reduced vaccination efficiency in these populations." (PMID 38329807, 2024). "IL1R2 and SPINK5 plays an important role in the diabetes mellitus and obesity." (PMID 36837510, 2023).
cervical cancer (4 papers, 2019 to 2024). A primary or metastatic malignant neoplasm involving the cervix. "Despite the limitations, this is the first work that concentrates on the polymorphisms of IL1R2 in correlation to cervical cancer risk in Uygur women from Northwest China." (PMID 30460760, 2019). "Our data first shed the new light on the associations of IL1R2 polymorphisms with cervical cancer susceptibility among Uygur females." (PMID 30460760, 2019). "In this study, we aimed to evaluate the relationships between IL1R2 polymorphisms and cervical cancer risk in Uygur females from China." (PMID 30460760, 2019). "Our results suggested the involvement of IL1R2 polymorphisms in the development of cervical cancer and provided new genetic markers for cervical cancer susceptibility assessment in the future." (PMID 30460760, 2019). "In this study, we performed a research to identify the risk variations in IL1R2 with an intention to better explore the characteristic predisposition of cervical cancer in Uygur women." (PMID 30460760, 2019). "Considerable associations were detected between IL1R2 rs719250, rs3218896 and cervical cancer among Uygur females." (PMID 30460760, 2019). "In this study, four SNPs in IL1R2 were demonstrated to be associated with cervical cancer in Uygur females, with protective or risky effects according to the genetic model and haplotype analysis." (PMID 30460760, 2019). "Furthermore, Genetic models and haplotype analyses were conducted to estimate the associations of IL1R2 polymorphisms with cervical cancer risk." (PMID 30460760, 2019). "Furthermore, the association between cervical cancer risk and haplotype of IL1R2 was analyzed in this work." (PMID 30460760, 2019). "The involvement of IL1R2 has also been reported in the progression of cervical cancer (Niu, Wang, Pei, & Li, 2017)." (PMID 30460760, 2019). "The imbalance of CDKN2A, IL1R2, and RFC4 could promote the proliferation of cancer cells, which is closely related to the progress of cervical cancer, and might be a potential diagnostic marker and therapeutic drug targets." (PMID 33833775, 2021). "These facts suggest distinct relationships among IL1R2, T‐cell activity, and cervical cancer." (PMID 30460760, 2019). "In addition, another researcher found that interleukin 1 receptor type 2 (IL1R2) is downregulated during the progression of cervical cancer." (PMID 31319555, 2019). "In our research, a case–control study was carried out to evaluate the effects of polymorphisms in IL1R2 on cervical cancer susceptibility among Uygur women from northwestern China for the first time." (PMID 30460760, 2019). "In this case–control study, genotypes of six selected variants (rs11674595, rs4851527, rs719250, rs3218896, rs3218977, and rs2072472) distributed in IL1R2 were detected among 247 cervical cancer patients and 286 healthy controls with the usage of an Agena MassARRY method." (PMID 30460760, 2019).
colitis (4 papers, 2012 to 2025). Inflammation of the colon. "Using an AOM/DSS-induced colitis-associated CRC model, we demonstrated that IL-1R2 deletion significantly reduces tumor burden." (PMID 40767963, 2025). "A similar model of DSS induced colitis investigated WT and IL1-R2 KO mice in which the KO mice exhibited less colon shortening, a clinical sign of disease." (PMID 31560732, 2019). "IL-1R exists in two forms, namely, IL-1R1 and IL-1R2, with IL-1R1 being the primary receptor, and IL-1R signaling directly induces chemokine expression and reactive oxygen species-generating genes, which have detrimental effects during epithelial injury-induced colitis." (PMID 40076032, 2025).
diabetes (4 papers, 2018 to 2024). "This association was independent of diabetes and liver fat (Beta = 0.26, p = 0.0053), but was attenuated (Beta = 0.17, p = 0.077) when also adjusting for circulating levels of interleukin-1 receptor type 2." (PMID 38795131, 2024).
gastric cancer (4 papers, 2021 to 2023). A primary or metastatic malignant neoplasm involving the stomach. "In gastric cancer, high expression of IL-1R2 in tumor tissue and increased levels of sIL-R2 in plasma were associated with poor prognosis." (PMID 35211118, 2022). "It has been proposed that increased IL1R2 levels are important during the initiation and progression of human gastric cancer." (PMID 36139698, 2022). "Increased levels of IL1R2 are involved in the initiation and progression of human gastric cancer, and IL1R2 might be an immunotherapeutic target." (PMID 37101794, 2023). "Moreover, gastric cancer ascites scRNA-seq analysis suggested that IL-1R2-expressing tumor cells contributed in tuning tumor-associated macrophage-dependent IL-1β-mediated inflammation." (PMID 35211118, 2022). "The present study was designedto investigate IL-1R2 expression in human gastric cancer (GC) tissues and theassociated clinical implications." (PMID 33704402, 2021).
Allergy (3 papers, 2015 to 2022). An allergy is an immune response or reaction to substances that are usually not harmful. "In contrast, the unique genes in the OTM group included Ddit3, Il1r2, Mmp9, Stfa2, and Stfa3, with the distinguishing feature of ‘allergy’ and ‘endopeptidase regulation’, which revealed the activation of macrophages after OTM." (PMID 35185928, 2022).
breast tumor (3 papers, 2020 to 2025). "IL1R2 promotes the self-renewal of breast tumor-initiating cells, as well as cancer proliferation and invasion." (PMID 35388653, 2022).
colon cancer (3 papers, 2022 to 2025). "Consistent with this notion, it was found that intracellular IL-1R2 enhanced the proliferation and migration of colon cancer cells by mediating the expression of cytokines, including VEGF and IL-615." (PMID 40767963, 2025). "However, the role of IL-1R2 in immune checkpoint blockade therapy for colon cancer remains largely unexplored." (PMID 40767963, 2025). "It has been reported that C-Fos, together with interleukin-1 receptor type 2 (IL1R2), promotes angiogenesis in human colon cancer cells to promote tumor progression." (PMID 36615849, 2022).
coronary artery disease (3 papers, 2011 to 2025). "IL1R2 may be involved in the immune and inflammatory responses associated with coronary artery disease (CAD)." (PMID 40231027, 2025). "For example, LFNG and ID3 were highly expressed in control samples, while ARG1 and IL1R2 were highly expressed in patients with coronary heart disease." (PMID 28903366, 2017). "To further evaluate the reliability of interaction relationships between disease-risk modules, we used the NCBI PubMed module to retrieve correlations between gene pairs and CAD with the term “GENE symbol 1+GENE symbol 2+coronary artery disease” (e.g. IL1R2+ESR2+coronary artery disease)." (PMID 21915342, 2011).
Crohn disease (3 papers, 2012 to 2024). A gastrointestinal disorder characterized by chronic inflammation involving all layers of the intestinal wall, noncaseating granulomas affecting the intestinal wall and regional lymph nodes, and transmural fibrosis. "Interestingly, GWAS have identified common IL1R2 variants as a key risk factor for UC and Crohn’s disease." (PMID 38329807, 2024). "Lower serum IL-1R2 was witnessed in both male and female patients with UC and Crohn’s disease." (PMID 38329807, 2024). "Finally, patients with UC or Crohn’s disease have lower serum IL-1R2." (PMID 38329807, 2024). "We also show substantially lower serum IL-1R2 in patients with either UC or Crohn’s disease but not vasculitis." (PMID 38329807, 2024).
Hodgkins lymphoma (3 papers, 2011 to 2021). A heterogeneous group of malignant lymphoid neoplasms of B-cell origin characterized histologically by the presence of Hodgkin and Reed-Sternberg (HRS) cells in the vast majority of cases. "Il1r2 was reported to be significantly elevated in the plasma of Hodgkin lymphomas' patients compared to healthy controls." (PMID 21747944, 2011). "Several lines of evidence indicate that the immunological function of IL-1 in Hodgkin’s disease is similarly inhibited, which may be partially explained by high amounts of soluble IL-1R2." (PMID 26406983, 2015).
IgA nephropathy (3 papers, 2017 to 2019). "In this study, we study the association between genetic variants of IL-1R1 and IL-1R2 and IgA nephropathy risk in the Chinese Han population." (PMID 28881593, 2017). "Many studies reported that the IL1R2 as a risk factor in some disease, such as IgA nephropathy." (PMID 30623603, 2019). "For example, previous study showed that the haplotype of IL1B, IL1RN, IL1R1, and IL1R2 increased the risk of venous thrombosis, and IL1/IL1Ra, CTLA-4 and Apo1/Fas genes polymorphisms associate with IgA nephropathy." (PMID 28881593, 2017).
lung adenocarcinoma (3 papers, 2019 to 2025). A carcinoma that arises from the lung and is characterized by the presence of malignant glandular epithelial cells. "An activated Treg signature, which includes IL-1R2 expression, as well as the IL1R2 gene itself, have been identified as independent prognostic markers associated with poor survival in lung adenocarcinoma." (PMID 41415279, 2025). "IL‐1R2 gene was downregulated in lung adenocarcinoma (LUAD, p < 0.01) and lung squamous cell carcinoma (LUSC, p < 0.01) based on GEPIA database." (PMID 30895747, 2019).
malaria (3 papers, 2014 to 2025). Malaria is a serious and sometimes fatal disease caused by a parasite that commonly infects a certain type of mosquito which feeds on humans. "In our analyses, IL1R2, LCN2, LTF, and MMP8 were associated with all SM subgroup comparisons to uncomplicated malaria." (PMID 40383794, 2025). "IL1R2 and FKBP5 have not been previously associated with malaria." (PMID 40383794, 2025). "In light of the reported association with septic shock, our associations of elevated IL1R2, LCN2, LTF, MMP8, and OLMF4 in SM subtypes compared to uncomplicated controls may reflect a general signature of the inflammatory reaction to severe infection and may not represent a malaria-specific pathway." (PMID 40383794, 2025).